PKD1 (polycystin 1, transient receptor potential channel interacting)
Diseases named in the same sentence as PKD1 in open-access papers (continued):
Sharing a sentence is not in itself a finding about the gene and the disease.
cyst (continued). "In Pkd1-deficient mice, aberrant expression of Wnt7a and Wnt7b was observed in cyst-lining cells, suggesting that upregulation of these ligands may initiate cystogenesis." (PMID 40801635, 2025). "Additionally, the timing of Pkd1 disruption has a dramatic impact on cyst formation, as early knockout causes significantly more severe disease than gene disruption in adult mice." (PMID 40722835, 2025). "Upregulated signaling pathways associated with cyst enlargement in 4 Pkd1 mouse models." (PMID 41122971, 2025). "While in the pancreas, detecting even a single cyst determines the probability of PKD1 versus PKD2 mutation, nearly all ADPKD subjects have liver cysts; the critical information is total liver cyst volume and liver cyst fraction, which are not substantially affected by missing small cysts." (PMID 39058059, 2024). "According to a “threshold model”, the cyst formation may be sustained by polycystin below a critical threshold because of PKD1 and/or PKD2 mutations, mutations of genes in the endoplasmic reticulum, or somatic mosaicism." (PMID 37834113, 2023). "Moreover, attenuating macrophage accumulation in Pkd1-deficient mice with Mcp1 knock-out or an antagonist of the MCP-1 receptor (also known as CCR2) reduced cyst growth and tubular injury." (PMID 36106024, 2022). "In Pkd1 mutant zebrafish, knocking down the core autophagy protein Atg5 caused inhibition of autophagy and promoted cystogenesis, while treatment with a specific inducer of Beclin-1 peptide activated autophagy and also slowed cyst growth." (PMID 35847973, 2022). "While an immortalized epithelial cell line derived from an ADPKD patient exhibited reduced c-Jun phosphorylation compared to control cells, cyst-lining epithelium with Pkd1 mutations in human and mouse kidneys expressed high levels of phosphorylated c-Jun and ATF2." (PMID 35253003, 2022). "Furthermore, we compared the efficiency of cyst formation in two human iPSC lines with different PKD1 mutations." (PMID 35629189, 2022). "Furthermore, reduced cyst formation was observed when forskolin or blebbistatin was added to the organoids developed from the hiPSC line with a different mutation MUi026-A: PKD1 gene (exon 15 with c.5878C>T), an hiPSC line we previously reported." (PMID 35629189, 2022). "A two-hit hypothesis suggests that cyst formation is triggered by somatic inactivation of functionally intact PKD in addition to germline mutation in either the PKD1 or PKD2 gene." (PMID 35629189, 2022). "Finally, we demonstrate that PKD1 or PKD2 derepression reverses cyst-pathogenic events in primary kidney cyst epithelia derived from individuals with ADPKD." (PMID 35965273, 2022). "Importantly, the loss of Cdk1 reduced cyst growth in a Pkd1 mutant kidney, making the Cdk1 pathway a strong candidate for the CDCA." (PMID 35253003, 2022). "Moreover, they validated these findings using iPSCs derived from a patient with a heterozygous mutation in the PKD1 gene, showing that UB organoids derived from the patient iPSCs evidenced robust cyst formation upon forskolin stimulation." (PMID 36120564, 2022). "This mimics the Pkd1 loss-of-function that underpins cyst formation in ADPKD." (PMID 33920158, 2021). "Therefore, NS398 inhibited cyst growth in both Pkd2 zebrafish and early‐onset Pkd1‐deficient mouse models and improved the renal function in early‐onset Pkd1‐deficient mouse model." (PMID 34551202, 2021). "In contrast to the Pkhd1-Cre model, deletion of PKD1 after postnatal day (PN) 14 leads to much slower cyst growth and loss of kidney function and, as a result, models in which PKD1 is inducibly deleted after PN day 14 are thought to more closely reflect disease in humans." (PMID 31260458, 2019). "In addition, MIF was upregulated in cyst-lining epithelial kidney cells of Pkd1-deficient mice as well as in the cyst fluid of human ADPKD kidneys." (PMID 31514750, 2019).
cyst (continued). "This difference may be related to their phenotypic differences: even though these two models showed similar cyst progression and timing of renal failure, Pkd2-deficient mice remained alive longer than Pkd1-deficient mice, for maximum of about 20 days." (PMID 29074972, 2017). "However, Pkd1 or Pkd2 conditional knockout mice, which are kidney-specifically deficient, are born normally and show rapid cyst formation from postnatal day 1 (P1), accompanied by increased cell proliferation by abnormal activation of the MAPK/ERK pathway." (PMID 29074972, 2017). "As mitochondrial damage is a main trigger for intracellular superoxide generation, we hypothesized that PKD1 mutations may occur in tubular cells harboring only a single wild-type allele in response to oxidative stress, leading to cyst formation." (PMID 28993480, 2017). "However, cyst-lining epithelial cells in Pkd1-deficient kidneys showed reduced and disorganized actin cytoskeletons with significantly decreased levels of marker genes such as Wasf2, Dock1, and Itga4." (PMID 29074972, 2017). "Finally, we examined the role of miR-17∼92 in a slow cyst growth model of ADPKD (Pkd1RC/RC) that harbours homozygous germline Pkd1 RC mutations." (PMID 28205547, 2017). "To verify whether the increase in renal Fetuin-A was related to cyst formation, we analyzed kidneys carrying a conditional Pkd1 allele that was deleted by tamoxifen-inducible KspCad-CreERT2." (PMID 25888842, 2015). "We also propose that postnatal kidney maturation is accompanied by changes in metabolic pathways that are likely to be modifiers of Pkd1-cystogenesis and could underlie the differences in the kinetics of cyst formation in early- or late-onset disease models." (PMID 23209428, 2012). "Using a mouse model of ADPKD carrying floxed Pkd1 alleles and an inducible Cre recombinase, we intensively analyzed the relationship between renal maturation and cyst formation by applying transcriptomics and metabolomics to follow disease progression in a large number of animals induced before P10." (PMID 23209428, 2012). "Transcriptomic analysis of the mouse model of ADPKD with PKD1 mutations of the rapid cyst-forming model, and human ADPKD, revealed a number of altered transcripts in cyst formation and suggests that metabolic changes may play a role in ADPKD and may accelerate disease progression." (PMID 36291168, 2022). "Since MUi026-A has a PKD1 point mutation (c.5878C > T) in contrast to the truncating mutation in MUi027-A (c.7946_7947delCT), the observed differences in the cyst formation could therefore represent the genotypic influences on the correlating phenotype development." (PMID 35629189, 2022). "To better model the disease in rodents and determine how acquired Pkd1 inactivation results in cyst formation, we had developed a novel mouse line with floxed alleles of Pkd1 that could be conditionally inactivated in a large proportion of kidney cells at distinct timepoints." (PMID 23209428, 2012). "Reduced dosage of PKD1 initiates cyst formation and drives progressive replacement of functional parenchyma, ultimately leading to kidney failure in many patients." (PMID 41558825, 2026). "We engineered three independent founder mouse lines with a targeted Pkd1 3′UTR mutation, each demonstrating PC1 stabilization and cyst suppression." (PMID 41558825, 2026). "Depletion of macrophages using liposomal clodronate has been demonstrated to reduce cyst growth and improve renal function in Pkd1fl/fl:Pkhd1-Cre mice (a model in which Pkd1 is specifically expressed in collecting ducts)." (PMID 41431718, 2026). "Using primary renal epithelial cells, engineered cell lines, and mouse models, we evaluated the impact of seed disruption or oligonucleotide masking on Pkd1/PKD1 mRNA stability, PC1 protein abundance, cyst growth, and downstream pathogenic programs." (PMID 41558825, 2026).
cyst (continued). "Together, these studies confirm the protective effect of a six-nucleotide substitution in the Pkd1 3′UTR in delaying cyst progression, and mitigating cyst-associated inflammation and fibrosis." (PMID 41558825, 2026). "These M2 macrophages, characterized by high arginase 1 (ARG1) expression, promote cyst enlargement in Pkd1−/− mice, suggesting ARG1 as a potential therapeutic target." (PMID 41431718, 2026). "First, although we demonstrate strong effects on transcript stability, protein restoration, and cyst growth in cultured cells, testing of the Pkd1-targeting oligonucleotide in mouse models of ADPKD remains to be performed." (PMID 41558825, 2026). "Our studies in Pkd1 mouse models demonstrate strong correlation of Kcnn4 expression status with cAMP/ERK/cMyc signaling in progression of cyst growth." (PMID 41122971, 2025). "Conditional Taz deletion in Pkd1-null mice reduced cyst growth and improved renal function, highlighting the PKD1–TAZ–β-catenin–c-Myc axis as a key therapeutic target in ADPKD." (PMID 40801635, 2025). "TMEM16a inhibitor CaCCinh-A01 (A01,10–30 μM) only minimally reduced cyst area in Pkd1–/– metanephroi." (PMID 41122971, 2025). "The structurally related KCa3.1 inhibitor TRAM-34, effective in cultured cells, also reduced cyst area of Pkd1–/– metanephroi by ~25%–30% at 20 and 40 μM." (PMID 41122971, 2025). "Site-specific gene editing techniques, such as CRISPR/Cas9, are commonly employed to generate homozygous or heterozygous mutations in PKD1 or PKD2, thereby modeling the genetic basis of cyst formation." (PMID 40002937, 2025). "Pkd1–/– metanephroi cultured in the presence of 20 μM senicapoc exhibited ~90% reduction in both cyst area and number." (PMID 41122971, 2025). "Cilia length changes in Pkd1 cko mice preceding cyst progression would argue for ciliary involvement preceding overt cystogenesis." (PMID 41474822, 2025). "The Osafune group took a similar approach, generating cyst-bearing PKD1+/- and PKD1-/- nephron organoids with the use of forskolin." (PMID 40722835, 2025). "Arginine restriction also appears to influence cyst growth; in in vitro studies, it has been shown that arginine deprivation can inhibit cyst growth, with PKD1-null cell lines exhibiting reduced proliferation under low-arginine conditions." (PMID 40722668, 2025). "Pkd1–/–;Kcnn4–/– metanephroi exhibited ~40% lower cyst area and ~30% lower cyst number than in Pkd1–/–;Kcnn4+/+ metanephroi, suggesting that KCa3.1 expression contributes not only to cyst enlargement but perhaps also to cystogenesis." (PMID 41122971, 2025). "Senicapoc (5 μM) addition to these Pkd1–/– metanephroi potentiated inhibition of cyst enlargement, as with A01." (PMID 41122971, 2025). "In ADPKD, treatment with a glutaminase inhibitor in PKD1-mutant mice, both in utero and postnatally, resulted in slowed cyst progression, highlighting the potential therapeutic benefit of targeting glutamine metabolism in ADPKD." (PMID 40722668, 2025). "Recent studies have identified specific methylation changes in ADPKD, including hypermethylation at the 3′ end of the PKD1 gene, which creates an environment conducive to cyst formation." (PMID 40801635, 2025). "Mutations in the PKD1/PKD2, which are responsible for ADPKD, affect intracellular signaling, including the mammalian target of the rapamycin (mTOR) pathway, leading to cyst formation and progression, while NF1 mutations overactivate the Ras proteins." (PMID 40051696, 2025). "There is a shift in energy production to excessive aerobic glycolysis in cyst cells in a murine model of PKD and human kidney cells with a PKD1 mutation." (PMID 40149611, 2025). "Pkd1–/– metanephroi underwent cyst growth for 72 hours (h) before 48h further supplementation with senicapoc or vehicle." (PMID 41122971, 2025). "As recently reported for a mouse model enabling both inactivation of Pkd1 or Pkd2 and subsequent gene reactivation, it was discovered that cyst formation is indeed (and somehow surprisingly) reversible." (PMID 39940890, 2025).
cyst (continued). "There is some indication that cell maturity and long-term growth can promote cyst formation, and monkeys with monoallelic PKD1 disruptions seem to confirm this." (PMID 40722835, 2025). "Small organoids containing 1–2 nephrons were generated on microwell patterned plates, enabling spontaneous cyst formation in PKD1-/- and PKD2-/- organoids." (PMID 40722835, 2025). "Genetic inactivation of Kcnn4 in rapidly and moderately progressive Pkd1 mouse models significantly delayed cyst growth, with substantial reduction in cellular, molecular, and physiologic hallmarks of PKD." (PMID 41122971, 2025). "Administration of KCa3.1 inhibitor senicapoc attenuated cyst growth and other indices of disease progression in all 4 tested Pkd1 mouse models of ADPKD." (PMID 41122971, 2025). "Studies showed that loss of pkd1 led to increased expression of TMEM16A and CFTR, as well as enhanced Cl− secretion in murine kidneys, with TMEM16A playing a key role in promoting cyst growth." (PMID 40136708, 2025). "Obacunone, a candidate compound for ADPKD drug development, has been shown to inhibit cyst formation and expansion in various cyst models, including a kidney-specific Pkd1-knockout mice model." (PMID 40806598, 2025). "Similar findings are seen in double knockout models involving Ift88 (also known as Tg737) and Pkd1, supporting the idea that cilia can promote cyst expansion when polycystins signaling is lost." (PMID 40801635, 2025). "SKA-111 treatment of Pkd1–/– metanephroi, already prone to larger cyst development, further increased cyst area ~34% and cyst number ~44% versus vehicle." (PMID 41122971, 2025). "This inactivation was phenocopied by exposure to KCa3.1 inhibitor, senicapoc, which nearly completely prevented cyst formation and growth in Pkd1–/– metanephroi." (PMID 41122971, 2025). "Our consistent findings of elevated renal cAMP content in tested Pkd1 mouse models reinforces original observations of increased cAMP in cultured human cyst epithelial cells and in the Pkd1RC/RC mouse model of ADPKD." (PMID 41122971, 2025). "Studies, both in vitro (using the Madin-Darby Canine Kidney (MDCK) cyst model) and in vivo (in a Pkd1 knockout mouse model), have demonstrated that curcumin and GB synergistically inhibit cyst formation and enlargement, which are hallmarks of ADPKD." (PMID 41300526, 2025). "In a mouse model permissive to the inactivation of Pkd1 or Pkd2 as well as subsequent gene reactivation, it was discovered that cyst formation is reversible, with cystic structures returning to normal nephrons." (PMID 39940890, 2025). "A notable example is the Pkd1 flox/− Ksp-Cre/− mouse, where the Ksp-Cre promoter drives the specific knockdown of Pkd1 in renal tubular epithelial cells during embryonic development, resulting in rapid cyst formation postnatally." (PMID 40002937, 2025). "Genetic and pharmacologic modulation in Pkd1-mutant mouse-derived metanephroi demonstrated that KCa3.1 upregulation induces and drives cyst formation and growth, whereas downregulation reduces cyst enlargement and even reverts previously formed cysts." (PMID 41122971, 2025). "Kcnn4 is expressed at E14.5 and E16.5 in developing Pkd1+/+ or Pkd1–/– kidneys, validating cultured metanephroi as an ex vivo experimental system in which to investigate KCa3.1 roles in cyst formation and enlargement." (PMID 41122971, 2025). "VX-809, a corrector of CFTR, was shown to slow cyst growth both in vivo and in vitro and improve the renal function in Pkd1−/− mice." (PMID 40136708, 2025). "In the current study, we adopted strategies to produce an unbiased discovery platform based on early tubule cell-specific transcriptional changes specifically related to the in vivo propensity for Pkd1-dependent cyst formation." (PMID 38693102, 2024). "Genetic knockout of SMYD3 in a PKD1 knockout mouse model delayed cyst growth and improved kidney function compared with PKD1 single knockout mouse kidneys." (PMID 38540216, 2024).
cyst (continued). "The depletion of macrophages can delay cyst growth and enhance renal function in Pkd1 mutant mouse kidneys." (PMID 39456148, 2024). "Mutations in PKD1 or PKD2 disrupt these signaling pathways, leading to uncontrolled cell proliferation and cyst formation." (PMID 39457411, 2024). "The microphage migration inhibitory factor (MIF) also regulates the recruitment of macrophages through TNF-α and monocyte chemoattractant protein-1 (MCP-1) and promotes cyst growth in Pkd1 mutant mouse kidneys." (PMID 39456148, 2024). "The disease is caused by mutations in PKD1 or PKD2 and is characterized by overproliferation of renal cells and uncontrolled cyst growth that leads to a loss in kidney function and renal failure." (PMID 38807632, 2024). "The drug was able to preferentially distribute in cysts in the kidney and collecting ducts, inhibiting miR-17 targets including Pkd1 and Pkd2 and effectively controlling cyst growth." (PMID 39802450, 2024). "Analysis of cyst size, number and cystic index identified significant improvements in all three measures induced by co-deletion of Pkd1 and Aurka." (PMID 38191531, 2024). "For example, the zebrafish pronephros consists of only two nephrons with a shared glomerulus and the pkd2 zebrafish model only forms one large cyst, in contrast to the more complex microenvironment of early cystic and non‐cystic tissue in iKsp‐Pkd1−/− mice." (PMID 38561249, 2024). "The knockout of SMYD3 in PKD1 mutant mouse kidneys induced cyst-lining epithelial cell apoptosis as analyzed by TUNEL (terminal deoxynucleotidyl transferase dUTP nick end-labeling) staining." (PMID 38540216, 2024). "Renal tubular cells of individuals carrying PKD1 or PKD2 mutations are likely more susceptible to DNA damage and aberrant apoptosis, which in turn facilitates spontaneous, cyst-initiating “second-hit” mutations in genes that include PKD1 and PKD2." (PMID 38474184, 2024). "Targeting STING with its specific inhibitor C-176 delays cyst growth in an early-stage aggressive Pkd1 conditional knockout mouse model and a milder long-lasting Pkd1 mutant mouse model." (PMID 39456148, 2024). "We show that knockout of CD74 ameliorates cyst growth and renal fibrosis in Pkd1 mutant mouse kidneys." (PMID 38534333, 2024). "We show that dysregulated/lost PC signaling induces not only nuclear translocation, but also the overexpression of MRTF in tubular cells and the cyst-lining epithelium in vitro and in PKD1 and 2 mutant animal models." (PMID 38891116, 2024). "We have reported that knockout of MIF and targeting MIF with its inhibitor, ISO-1 delayed cyst growth in Pkd1 knockout mouse models." (PMID 38534333, 2024). "These conclusions are supported by our in vivo data showing that genetic deletion of C3 significantly slows cyst development in Pkd1–/– mice." (PMID 38912583, 2024). "HL156A was administered orally on P2, before cyst formation, and then, the collecting duct-specific Pkd1 KO mice were sacrificed on P28 to measure BUN levels." (PMID 39062520, 2024). "Inactivation of Glis2 in early onset and adult mouse models of Pkd1 and Pkd2 resulted in suppression of cyst formation." (PMID 38693102, 2024). "The Pkd1 hypomorphic Pkd1nl/nl mouse has been reported to develop interstitial fibrosis during cyst progression." (PMID 38534333, 2024). "Despite differing mechanisms from Pkd1 and Pkd2 mutations in ADPKD, PKHD1 mutations similarly disrupt renal cell signaling and structural integrity, leading to cyst formation primarily in the collecting ducts of the kidneys and often affecting the liver." (PMID 39802450, 2024). "This compound has been shown to increase Pkd1/Pkd2 expression and reduce cyst growth in CRISPR-edited cellular and mouse models of ADPKD." (PMID 39595570, 2024). "The promotion of cyst growth was attributed to downregulated PKD1-mRNA and increased levels of miRNAs of the miR-200 family." (PMID 36399151, 2023).